RNASET2 (ribonuclease T2)
Diseases named in the same sentence as RNASET2 in open-access papers (continued):
Sharing a sentence is not in itself a finding about the gene and the disease.
breast carcinoma (3 papers, 2023 to 2025). "Pathways identified in CXCL12 and FB2 fibroblast cell clusters from RA and in the B2 cell cluster from HER2+ breast cancer patients support that TMEM230/RNASET2/SDC2/IRF1 axis have pleiotropic functions." (PMID 40862725, 2025). "We therefore investigated the possible role of RNASET2 with IRF1 in breast cancer." (PMID 40862725, 2025). "As we previously identified that many of these pathways in gliomas of patients were associated with aberrant expression of TMEM230 and RNASET2, in our current study we investigated whether these pathways would also be identified in fibroblast clusters of HER2+ breast cancer patients." (PMID 40862725, 2025). "In this study, we identified expression patterns of IRF1, TMEM230, RNASET2, and syndecan 2 (SDC2) in different cell types of breast cancer patients using single-cell mRNA transcript analyses." (PMID 40862725, 2025).
clear cell renal cell carcinoma (3 papers, 2023 to 2024). "In clear cell renal cell carcinoma, high RNASET2 expression is linked to poor prognosis, with its silencing inhibiting the migration capacity and pro-angiogenesis of renal cancer cells." (PMID 39035989, 2024). "RNASET2 has been identified as an oncogene with anti-angiogenic and immunomodulatory effects in a variety of cancers, but its function in clear cell renal cell carcinoma (ccRCC) is still not well understood." (PMID 37679715, 2023). "RNASET2 expression in 74 pairs of clear cell renal cell carcinoma compared with adjacent normal tissues." (PMID 36728187, 2023).
gastric cancer (3 papers, 2021 to 2025). A primary or metastatic malignant neoplasm involving the stomach. "In our previous study, these methods were employed to confirm that RNASET2 was neither a tumor suppressor gene nor an oncogene in gastric carcinoma." (PMID 35003516, 2021).
lysosomal storage disease (3 papers, 2018 to 2020). A metabolic disorder caused by mutations in proteins critical for lysosomal function, including lysosomal enzymes, lysosomal integral membrane proteins, and proteins involved in the post-translational modification and trafficking of lysosomal proteins. "In zebrafish, the loss of RNASET2 gene function induces a lysosomal storage disorder in distinct populations of myeloid cells, probably by a cell autonomous mechanism, as we show here." (PMID 32295832, 2020). "Loss-of-function mutations in human RNASET2 lead to familial cystic leukoencephalopathy, which is considered as a lysosome storage disease, but how lysosomal rRNA accumulation leads to neuronal disease is unclear." (PMID 30102152, 2018). "Together, these results indicate that RNASET2-deficient cystic leukoencephalopathy is a lysosomal storage disorder, in which RNA species may be the noxious storage material provoking an inflammatory reaction similar to congenital CMV infection." (PMID 32295832, 2020). "From our previous study on zebrafish we concluded that RNASET2-deficient cystic leukoencephalopathy could be a lysosomal storage disorder, in which rRNA species are the best candidate for the noxious storage material." (PMID 32295832, 2020). "Loss of RNASET2 may therefore cause a lysosomal storage disorder." (PMID 29752287, 2018). "Indeed, it has been hypothesized that cystic leukoencephalopathy without megalencephaly, caused by loss of RNASET2 function, is a lysosomal storage disease, with accumulation of excess RNA eliciting an autoimmune and neuroinflammatory response akin to what is observed in CMV and AGS." (PMID 29752287, 2018).
megalencephaly (3 papers, 2018 to 2026). A congenital abnormality in which the occipitofrontal circumference is greater than two standard deviations above the mean for a given age. "Studies of the rare autosomal recessive disorder cystic leukoencephalopathy without megalencephaly caused by RNaseT2 mutations describe clear neuroradiological signs similar to congenital cytomegalovirus (CMV) brain infection." (PMID 29752287, 2018).
ovarian tumor (3 papers, 2020 to 2023). "For example, RNASET2 expression is down-regulated in various ovarian tumor and cancer cell lines, and its introduction into cells exerts tumor suppressive effects both in vivo and in vitro." (PMID 37679715, 2023). "Up-regulation of RNASET2 expression induced tumor cell senescence and inhibited the tumorigenicity of the ovarian tumor in nude mice model." (PMID 32528897, 2020). "RNASET2 protein expression was significantly decreased in a large proportion of ovarian tumor cell lines." (PMID 32528897, 2020).
renal carcinoma (3 papers, 2022 to 2024). A carcinoma arising from the epithelium of the renal parenchyma or the renal pelvis. "Consistent with the upregulation of mRNA levels, RNASET2 protein expression was significantly upregulated in renal cancer tissues (patient numbers: 1831, 3039 and 3616) compared to normal tissues (patient numbers: 1767, 2530 and 3356)." (PMID 37679715, 2023). "Secondly, the effect of RNASET2 on the malignant behavior of renal cancer cells has only been explored in in vitro experiments and evidence from in vivo experiments needs to be refined in subsequent experiments." (PMID 37679715, 2023). "RNASET2 expression was significantly upregulated in ccRCC tissues and renal cancer cell lines, predicting poor prognosis for patients." (PMID 37679715, 2023). "RNASET2 mRNA expression was detected by quantitative polymerase chain reaction (qPCR) in ccRCC patients and renal cancer cell lines." (PMID 37679715, 2023). "Protein expression levels of RNASET2 in renal carcinoma were obtained from immunohistochemical staining data from the HPA database (antibody, HPA066509)." (PMID 37679715, 2023). "In vitro experiments showed that silencing RNASET2 inhibited the migration and pro-angiogenic ability of renal cancer cells." (PMID 37679715, 2023). "Wound healing assay, transwell assay, western blotting, and tube formation assays were used to evaluate the function of RNASET2 in renal cancer in vitro." (PMID 37679715, 2023). "However, inconsistent with previous findings, the angiogenic capacity of HUVECs was significantly reduced after treatment with culture medium supernatant from renal cancer cells (A498, 786-O) following RNASET2 siRNA intervention relative to the si-NC group." (PMID 37679715, 2023). "Furthermore, silencing of RNASET2 inhibited migration of renal cancer cells and angiogenesis in the tumor microenvironment." (PMID 37679715, 2023). "Mechanistically, its pro-cancer effects may depend on the promotion of renal cancer cell migration, angiogenesis, and remodeling of the immune microenvironment of RNASET2." (PMID 37679715, 2023). "Moreover, the immune microenvironment and mutational status were evaluated to predict the potential mechanisms of RNASET2 involvement in renal cancer progression." (PMID 37679715, 2023). "Here, through transcriptome sequencing analysis of si-RNASET2(si-2) and si-NC treated renal cancer cells and subsequent exploration of biological mechanisms, we found that RNASET2 may be involved in the regulation and remodeling of the immune microenvironment in renal cancer to some extent." (PMID 37679715, 2023). "However, some of these genes, such as RNASET2, TF, and ZIC2, were already known to have an oncogenic role in the tumorigenesis, progression, and metastasis of renal cancer." (PMID 36463181, 2022).
rheumatoid arthritis (3 papers, 2018 to 2025). A chronic, systemic autoimmune disorder characterized by inflammation in the synovial membranes and articular surfaces. "We previously demonstrated that TMEM230 and RNASET2 were downregulated in CXCL12 expressing synovial fibroblast cells of rheumatoid arthritis (RA) compared to osteoarthritis (OA) patients." (PMID 40862725, 2025). "As this list includes eQTLs such as RNASET2 and ADO, which have not been previously linked to rheumatoid arthritis, this approach might be effective for identifying disease associated eQTL-SNPs." (PMID 29740473, 2018).
Cerebral atrophy (2 papers, 2021 to 2025). Atrophy (wasting, decrease in size of cells or tissue) affecting the cerebrum. "RNaseT2-deficient cystic leukoencephalopathy (CLE) presents with severe psychomotor retardation, cystic brain lesions, white matter alterations, and cerebral atrophy." (PMID 41453865, 2025).
cytomegalovirus infection (2 papers, 2020 to 2026). A herpesvirus infection caused by Cytomegalovirus. "Human patients suffering from the loss of functioning RNASET2 present with clinical manifestations resembling a cytomegalovirus infection and therefore suggesting an important role for the immune system in the pathology of the disease." (PMID 32212285, 2020).
hepatocellular carcinoma (2 papers, 2023 to 2025). A malignant tumor that arises from hepatocytes. "The results showed that RNASET2 was aberrantly highly expressed in a variety of cancers, including kidney, lung, breast and hepatocellular carcinomas." (PMID 37679715, 2023).
Hydrocephalus (2 papers, 2019 to 2023). Hydrocephalus is an active distension of the ventricular system of the brain resulting from inadequate passage of CSF from its point of production within the cerebral ventricles to its point of absorption into the systemic circulation. "Interestingly, Ferris and colleagues reported a 7% reduction in cortical volume in the R222 RNaseT2 KO rat with severe spontaneous hydrocephalus." (PMID 37350791, 2023). "If the RNAse T2 mutation is not the cause of the hydrocephaly mutation is it possible the absence of RNAseT2 is responsible for the longevity of R222?" (PMID 31712649, 2019).
kidney cancer (2 papers, 2023). Primary or metastatic malignant neoplasm involving the kidney. "First, with the help of subcellular fractionation experiments, we determined that RNASET2 expression was mainly located in the cytoplasm of kidney cancer cells (A498, 786-O)." (PMID 37679715, 2023). "This implies that RNASET2 can promote the EMT process in kidney cancer cells to some extent, which is also consistent with the results of cell migration assays." (PMID 37679715, 2023). "CCLE reveals that the expression of RNASET2 is significantly higher in kidney cancer than that in other cancers." (PMID 36728187, 2023). "Next, we treated A498 and 786-O cells with siRNA to knock down RNASET2 expression in the kidney cancer cell lines and validate its knockdown efficiency, accompanied by subsequent functional assays." (PMID 37679715, 2023).
neuroendocrine lung neoplasms (2 papers, 2023). "On the contrary, RNASET2 expression is significantly higher in poorly differentiated cancer cells than that in the well‐differentiated cancer cells in neuroendocrine neoplasms of the lung." (PMID 36728187, 2023). "On the other hand, in other cancer types, such as neuroendocrine lung neoplasms (Lu-NENs), RNASET2 expression was found to be upregulated in high-grade tumor samples." (PMID 37626657, 2023).
pancreatic cancer (2 papers, 2024 to 2025). "In the course of cancer therapy, PDIA5 can interact with RNASET2 to resist the killing ability of drugs on pancreatic cancer cells." (PMID 39247813, 2024).
viral infections (2 papers, 2021 to 2025). "A better understanding of the functional consequences of type I interferon-triggered pathways within the CNS will have far-reaching implications not only for inborn RNaseT2-deficient CLE and AGS but also for congenital viral infections." (PMID 34764281, 2021). "While RNASET2 like IRF1 is closely linked with immune responses in viral infections and like IRF1 is thought to have a role in cancer, RNASET2 was not identified coregulated with IRF1 in FB2 cells." (PMID 40862725, 2025).
Adult T-cell leukemia (1 paper, 2020). "Human T-cell Leukemia Virus type 1 (HTLV-1), the pathogen of Adult T-cell leukemia (ATL), encodes a protein Tax and is found to inhibit RNase T2 expression by occupying RNASET2 gene promoter." (PMID 32903619, 2020).
amyotrophic lateral sclerosis (1 paper, 2018). Amyotrophic lateral sclerosis (ALS) is a neurodegenerative disease characterized by progressive muscular paralysis reflecting degeneration of motor neurons in the primary motor cortex, corticospinal tracts, brainstem and spinal cord. "Indeed, we find examples of genetic deficiencies in extracellular RNases that lead to immune-related diseases, such as amyotrophic lateral sclerosis (ALS), associated with human RNase5 mutations and cystic leukoencephalopathy, a neuronal disorder associated with RNaseT2 deficiency." (PMID 29867984, 2018).
Arthritis (1 paper, 2024). Inflammation of a joint. "We found that the serum levels of RNASET2 were elevated after the induction of the two arthritis models, correlating with the onset and establishment of the disease." (PMID 39500942, 2024). "We demonstrate that RNASET2 is expressed in PMN and macrophages infiltrating the murine joints at the peak of K/BxN serum-transfer-induced arthritis, which models the effector phase of human RA." (PMID 39500942, 2024). "The highest circulating levels of RNASET2 were observed at the peak phase of disease severity and declines in the late stages in CIA and more rapidly in the STIA model paralleling the clinical features of the experimental arthritis." (PMID 39500942, 2024). "Given the increased expression within rheumatoid synovial tissue, we expanded the study to look at RNASET2 serum concentrations in STIA and CIA experimental murine RA models, which are feasible for studying immune system alterations during arthritis development." (PMID 39500942, 2024).
breast tumors (1 paper, 2025). "We therefore investigated the possible pathways regulated by RNASET2 in other cell types found in HER2+ breast tumors." (PMID 40862725, 2025). "Largest difference in the expression of RNASET2 between control and HER2+ breast tumors was observed in the uncharacterized epithelial EPI2 cell clusters and in clusters associated with immune functions such as B, natural killer (NK) and plasma cells." (PMID 40862725, 2025). "In agreement with its role in immune cell function, RNASET2 was downregulated or absent in EPI2 epithelial cell cluster in HER2+ breast tumors, as seen for the expression pattern of IRF1." (PMID 40862725, 2025).
Cognitive impairment (1 paper, 2018). Abnormal cognition is characterized by deficits in thinking, reasoning, or remembering. "In summary, our studies show that the RNaseT2 KO rats exhibit hippocampal neuroinflammation and signs of cognitive impairment, which may be driven by lysosomal dysfunction." (PMID 29752287, 2018).
cystic leukoencephalopathy without megalencephaly (1 paper, 2013). Cystic leukoencephalopathy without megalencephaly is characterized by non-progressive leukoencephalopathy, bilateral cysts in the anterior part of the temporal lobe, cerebral white matter anomalies and severe psychomotor impairment. "Defects in RNASET2 are proposed to be the cause of cystic leukoencephalopathy without megalencephaly (LCWM), and the brain of such affected individuals shows anterior temporal lobe subcortical cysts." (PMID 23628075, 2013).
Dystonia (1 paper, 2020). An abnormally increased muscular tone that causes fixed abnormal postures. "RNAseT2‐deficient patients present with severe locomotor disabilities, including spasticity and dystonia, which arise in the first year of the patient life." (PMID 32212285, 2020).
epilepsy (1 paper, 2018). A brain disorder characterized by episodes of abnormally increased neuronal discharge resulting in transient episodes of sensory or motor neurological dysfunction, or psychic dysfunction. "Motor behavior testing was also performed in 12-month-old animals since RNASET2-deficient patients exhibit psychomotor impairment, spasticity and epilepsy." (PMID 29752287, 2018). "RNASET2 deficiency in humans is associated with infant cystic leukoencephalopathy, which causes psychomotor impairment, spasticity and epilepsy." (PMID 29752287, 2018). "Children with RNASET2 deficiency present with mental and motor retardation and oftentimes epilepsy." (PMID 29752287, 2018).
GM2 gangliosidosis (1 paper, 2018). A group of recessively inherited diseases characterized by the intralysosomal accumulation of G(M2) GANGLIOSIDE in the neuronal cells. "Future studies that quantify brain gangliosides in RNaseT2 KO rats will further determine the translatability to related conditions (e.g. GM1 and GM2 gangliosidosis) found in patients." (PMID 29752287, 2018).
lung adenocarcinoma (1 paper, 2024). A carcinoma that arises from the lung and is characterized by the presence of malignant glandular epithelial cells. "There were 5 genes with a causal relationship to lung adenocarcinoma, including RNASET2, MPZL2, MPZL3, CHRNA5 and UCKL1." (PMID 38834983, 2024).
malignant neoplasms of the skin (1 paper, 2024). "BCC, malignant neoplasms of the skin, and gastrointestinal endpoints (KELA_REIMBURSEMENT_202) emerged as the three most significant phenotypes out of 9,621 protein-phenotype pairs, which were significantly associated with RNASET2 in the UKB-PPP study." (PMID 39035989, 2024).
metastasis (1 paper, 2020). The spread or migration of cancer cells from one part of the body (where they first appeared) to another. "The expression of RNASET2 in GAC was not related to angiogenesis, lymph nodal metastasis, and patients' prognosis." (PMID 32528897, 2020).
metastatic tumors (1 paper, 2020). "In addition, we randomly selected 27 cases of advanced GAC patients with lymph nodal metastasis from another cohort, and then detected RNASET2 protein expression between the primary tumor and lymph nodal metastatic tumor in GAC." (PMID 32528897, 2020). "Furthermore, we also found that the positive rate of RNASET2 protein expression was the same between the primary tumors and lymph nodal metastatic tumors in GAC." (PMID 32528897, 2020).
microcephaly (1 paper, 2018). A congenital or acquired developmental disorder in which the circumference of the head is smaller than normal for the person's age and sex. "Mutations in RNASET2 are associated with an autosomal recessive disorder characterized by early-onset severe developmental disorders, usually microcephaly, seizures, and sometimes hearing impairment." (PMID 29740383, 2018).
prostate carcinoma (1 paper, 2025). A carcinoma that arises from epithelial cells of the prostate gland. "To evaluate the clinical impact of RNASET2 expression levels on the survival of prostate cancer (PCa) patients, we performed an in-silico analysis using the cSurvival online tool, using available datasets." (PMID 40389981, 2025). "Our findings were further supported by an extensive in silico analysis and strongly indicated that RNASET2’s established tumor-suppressive role extends to at least a subset of prostate cancer types." (PMID 40389981, 2025). "The human RNASET2 protein has demonstrated both oncosuppressive and immunoregulatory functions across various cancer types, yet its role as an oncosuppressor or alarmin-like molecule in prostate cancer (PCa) is unexplored." (PMID 40389981, 2025). "To further assess at the functional level the impact of RNASET2 on the macrophage cell lineage in the context of prostate cancer, we employed a co-culture approach (entailing a direct cell-to-cell contact) to mimic the RNASET2-mediated cancer cell/macrophage functional crosstalk occurring in vivo." (PMID 40389981, 2025). "This suggests that RNASET2-overepressing 22Rv1 cells might strongly shape a different macrophage-oriented and tumor suppressive TME, compared with RNASET2-overepressing PC-3 cells, in turn possibly impacting on prostate cancer cell growth in-vivo." (PMID 40389981, 2025). "This study is to our knowledge the first to demonstrate the tumor-suppressive role of human RNASET2 in prostate cancer, acting through both cell-autonomous mechanisms and non-cell-autonomous pathways, particularly by promoting M1-like macrophage polarization." (PMID 40389981, 2025).